HLA-G (major histocompatibility complex, class I, G)
Diseases named in the same sentence as HLA-G in open-access papers (continued):
Sharing a sentence is not in itself a finding about the gene and the disease.
preeclampsia (continued). "Previously, SNPs in the 3′UTR region of HLA-G have been evaluated in terms of preeclampsia pathophysiology, which showed diverse results." (PMID 29540242, 2018). "The low level of sHLA-G in primigravid women is consistent with the fact that preeclampsia, more prevalent in first-time pregnancies, has been found frequently associated with a decreased level of soluble HLA-G." (PMID 28166246, 2017). "The abnormal methylation of HLA-G gene has been found in cancers and preeclampsia; and hypermethylation of HLA-A, B, C was observed in esophageal squamous cell carcinoma (ESCC)." (PMID 27713139, 2017). "Many studies have examined the HLA-G soluble in a variety of disorders such as preeclampsia, tumors, autoimmune diseases, and abortion; studies have also been conducted in the area of diabetes which mostly included diabetes type I and type II." (PMID 27757202, 2016). "In this review, a genetic contribution from the mother, the father, and the fetus, together with the presence and function of various immune cells of relevance in pregnancy are reviewed in relation to HLA-G and preeclampsia." (PMID 25566263, 2014). "The review will also highlight important and partly conflicting observations regarding HLA-G genetics and HLA-G expression in preeclampsia that further research needs to address." (PMID 24741608, 2014). "While the beneficial role of HLA-G is recognized in relation to pregnancy, a precise relationship between HLA-G and preeclampsia needs further appraisal." (PMID 25566263, 2014). "Much effort has been put into clarifying the role of HLA-G during pregnancy and pregnancy complications, such as preeclampsia, recurrent spontaneous abortions, and subfertility or infertility." (PMID 24741608, 2014). "This is in accordance with a study of HLA-G mRNA expression in preeclampsia, in which a high expression of HLA-G5 mRNA was detected in preeclampsia compared to controls." (PMID 24741608, 2014). "An increasing number of studies have indicated a role for HLA-G in the pathogenesis of preeclampsia." (PMID 24741608, 2014). "In relation to a possible importance of HLA-G expression in the pathogenesis of preeclampsia, it is important to study the influence of the HLA-G polymorphisms in the 5′URR and the 3′UTR on transcription, mRNA stability, and alternative splicing." (PMID 24741608, 2014). "In normal pregnancy, the prevalence of CD4+HLA-G+ T cells is high in decidua, while a recent study showed that the expansion of the HLA-G-positive T cell subset is impaired in preeclampsia." (PMID 25566263, 2014). "Decreased levels of HLA-G have been reported in the circulation of women with preeclampsia and reduced cell-surface expression has been reported in trophoblasts." (PMID 21569342, 2011). "Although various immune and metabolic pathways have been proposed in late-onset preeclampsia (LO-PE), direct evidence for specific processes—such as Allograft Rejection, Estrogen Response, or Glycolysis—and for genes like HLA-G, IL17RB, and KLRC4 remains limited." (PMID 40427999, 2025). "Maternal allele frequencies for all SNP loci of the KIR2DL4 gene and HLA-G gene were not significantly different between the preeclampsia group and the control group." (PMID 39144721, 2024). "Soluble HLA-G, involved in maternal–fetal immune tolerance, may serve as a marker for impaired immune responses in preeclampsia." (PMID 38674114, 2024). "Combined with our findings, we believe that fetal HLA-G contributes more to the establishment of maternal-fetal tolerance and therefore may be more relevant to the pathological mechanisms of preeclampsia." (PMID 39144721, 2024). "Pregnancy complications (e.g., miscarriage, preterm delivery, preeclampsia, and recurrent pregnancy loss(RPL)) have been reported to be associated with naturally occurring HLA-G polymorphisms that may trigger lower HLA-G levels." (PMID 38418860, 2024).
preeclampsia (continued). "Besides aberrations in CD31+ cells, other potential biomarkers such as MMPs, soluble HLA-G, and hCG hold promise for predicting preeclampsia and its complications." (PMID 38674114, 2024). "Among the four SNP loci in the fetal HLA-G gene, the frequencies of rs9380142A (OR = 2.802, 95% CI = 1.761∼4.458, p = 0.001) and rs1063320G (OR = 1.807, 95% CI = 1.144∼2.852, p = 0.01) were greater in the preeclampsia group than in the control group." (PMID 39144721, 2024). "Decreased HLA-G RNA and protein levels have been found in a subset of preeclampsia patients." (PMID 38674114, 2024). "The mechanism by which HLA-G is decreased in preeclampsia is undefined." (PMID 35571013, 2022). "Several studies reported that abnormal sHLA-G expression is associated with pregnancy complications such as preeclampsia, recurrent miscarriage (RM), and recurrent implantation failure (RIF), and may be further linked to HLA-G polymorphisms." (PMID 36532068, 2022). "Since preeclampsia is an angiogenesis defect disease and is well known for the ‘two-stage’ hypothesis under oxidative stress, HLA-G also has an effect on preeclampsia with low expression and 14bp ins/del polymorphism." (PMID 34777357, 2021). "Therefore, it will accelerate the treatment and prevention of preeclampsia to investigate the role of HLA-G in spiral artery remodeling." (PMID 33193435, 2020). "In this study, genomic sequences of the HLA-G region (5.2 kb) from 31 pairs of mother–offspring genomic DNA samples (18 pairs from normal pregnancies/births and 13 from preeclampsia births) were obtained by single-molecule real-time sequencing using the PacBio RS II platform." (PMID 33208885, 2020). "miR-1301 is known to be dysregulated in early-onset preeclampsia, similar to HLA-G." (PMID 32019184, 2020). "Their results did not reveal any association between the HLA-G 14-bp polymorphism and the risk of preeclampsia." (PMID 30893814, 2019). "The authors speculated that the reduced IL-10 levels observed in preeclampsia may lead to reduced HLA-G and ILT4 expression and impaired tolerogenic activity of these CD14+DC-SIGN+ APCs." (PMID 29686676, 2018). "Therefore, our study was meaningful because we analyzed and compared SNPs in the 3′UTR of HLA-G between placentas with spontaneous preterm birth and those with preeclampsia." (PMID 29540242, 2018). "Therefore, the aim of the present study was to compare SNPs in the 3′UTR of the HLA-G between pregnancies complicated with spontaneous preterm births and those with preeclampsia in gestational age matched placentas." (PMID 29540242, 2018). "Due to their role as key regulators in placentation and subsequent pregnancy outcome, low blood concentrations of soluble HLA-G (sHLA-G) and PAPP-A have been associated with increased risks of miscarriage, preeclampsia, hypertension, and intrauterine growth restriction." (PMID 28655969, 2017). "Given that shedded sHLA-G1 levels seem to be lower in blood plasma of pregnant women with severe preeclampsia in late pregnancy it can be speculated that HLA-G1 might be the most important source of HLA-G in the pathogenesis of preeclampsia." (PMID 24741608, 2014). "Several studies have linked HLA-G genotypes and aberrant HLA-G protein expression to preeclampsia; however, other studies have not obsered any significant associations." (PMID 24741608, 2014). "Also, HLA-G is secreted by erythroblasts, which is interesting as increased fetal erythroblastosis is detected in women who subsequently develop preeclampsia." (PMID 25566263, 2014). "In placental tissue, a reduced expression of HLA-G has been linked to preeclampsia, but these studies did not differentiate between membrane-bound HLA-G and sHLA-G; and most of these studies did not examine a possible association with the 14 bp polymorphism." (PMID 24741608, 2014). "However, direct effects of HLA-G on immune cell activation, recruitment, and function in the context of preeclampsia remain to be elucidated." (PMID 25566263, 2014).
preeclampsia (continued). "The Human Leukocyte Antigen (HLA)-G is an increasing focus of research in relation to preeclampsia." (PMID 25566263, 2014). "Furthermore, we highlight important observations regarding HLA-G genetics and expression in preeclampsia that future research should address." (PMID 24741608, 2014). "An association between HLA-G haplotypes and preeclampsia has been reported in some studies but not in all." (PMID 25566263, 2014). "Taken together, whether HLA-G genotypes and expression patterns might have a significant influence on the development of preeclampsia remains controversial." (PMID 25566263, 2014). "Also, soluble HLA-G, involved in maternal–fetal immune tolerance, is reduced in preeclampsia." (PMID 38674114, 2024). "Moreover, HLA-G expression by extravillous trophoblasts, which promotes vascular remodeling, may help ensure successful placentation thus preventing preeclampsia." (PMID 33995358, 2021). "Thus, it is not surprising that loss of HLA-G may result in adverse pregnancy outcomes such as preeclampsia, unsuccessful embryo implantation, and fetal loss." (PMID 39355248, 2024). "Some authors reported that elevated HLA-G expression found in severe preeclampsia cases may reflect undifferentiated status of EVTs and that EVTs from a full-term placental bed having reduced invasive capacity also have a decreased ability to up-regulate HLA-G protein expression." (PMID 38473890, 2024). "A significant reduction in the expression of HLA-G and ILT4 on decidual APCs is observed in preeclampsia compared with normal pregnancy, providing a possible clue to the lack of iTregs in preeclampsia." (PMID 32676072, 2020). "Altered expression of the HLA-G NK cell ligand has also been reported to have a significant influence on IFN-γ production by NK cells and development of preeclampsia." (PMID 25243172, 2014). "Interestingly, a study found that the HLA-G mRNA profile in term placental biopsies is shifted toward a higher frequency of HLA-G5 in preeclampsia, which is supported by higher HLA-G5 protein levels in maternal blood in preeclampsia compared to controls according to another, independent study." (PMID 25566263, 2014). "The non-classical HLA class I molecules HLA-F and HLA-G have also been identified as potentially dysregulated in preeclampsia." (PMID 35571013, 2022). "They hypothesized that HLA-G 3′UTR SNP-pair associations, and not individual SNPs, could be useful to predict susceptibility to preeclampsia." (PMID 27652273, 2016).
viral infections (47 papers, 2010 to 2025). "Although HLA-G expression is typically associated with the maternal–fetal interface, it is also upregulated in areas of inflammation, after viral infection, and in response to certain cytokines." (PMID 39105878, 2024). "In this review, the expression, regulation, and clinical impact of HLA-G neoexpression in the context of viral infections as well as the underlying molecular mechanisms will be summarized." (PMID 35237271, 2022). "Recently, evidence accumulated that HLA-G is an emerging susceptibility and/or protection relevant factor for unresolved virus infection and viral resistance." (PMID 36334153, 2022). "This review focuses on the role of HLA-G genetic polymorphisms, mRNA, and protein expression in autoimmune conditions and viral infections." (PMID 25477881, 2014). "Aberrant HLA-G expression has been closely associated with several pathological conditions, including transplantation, autoimmune and inflammatory diseases, viral infections, and malignancies." (PMID 24870375, 2014). "However, SARS-CoV-2 infection, like other viral infections, can cause a marked variation in sHLA-G levels due to inflammation and upregulation of immune inhibitory receptors of which HLA-G is a ligand." (PMID 37342325, 2023). "Impact of HLA-G polymorphisms on viral infections and virus-mediated diseases." (PMID 35237271, 2022). "Increased knowledge of the link between HLA-G expression, viral infection and disease progression is urgently required, which highlights the possible use of HLA-G as novel diagnostic and prognostic biomarker for viral infections, but also as therapeutic target." (PMID 35237271, 2022). "Therefore, this review aims to summarize the expression, regulation, function and impact of HLA-G in the context of different viral infections including virus-associated cancers." (PMID 35237271, 2022). "In addition, the pathophysiologic neo-expression of HLA-G surface antigens and of sHLA-G isoforms in tumors or upon viral infections was associated with disease progression, poor clinical outcome, and adverse therapy response of patients." (PMID 36334153, 2022). "HLA-G is also associated with progression of tumours and viral infections." (PMID 25115633, 2014). "Indeed, concentrations of soluble HLA-G in the blood increase in some viral infections caused by HIV, hCMV, HCV, and HBV viruses, similar to classical soluble class I antigens." (PMID 24839609, 2014). "HLA-G has been associated with these viral infections and this could influence our results." (PMID 28166246, 2017). "HLA-G gene is characterized by polymorphisms at the 3′ un-translated region and 5′ upstream regulatory region that regulate its expression and are associated with autoimmune diseases and viral infection susceptibility, creating an unbalanced and pathologic environment." (PMID 25477881, 2014). "There are known associations between high levels of circulating soluble HLA-G (sHLA-G) and either parasite or viral infections and it has been suggested that the induction of sHLA-G expression could be a mechanism via which infectious agents subvert host immune defence." (PMID 25115633, 2014). "The expression of HLA‐G is restricted to certain tissues under physiological conditions, but is upregulated during pregnancy and in pathological conditions such as tumours, viral infections and inflammatory diseases." (PMID 40910405, 2025). "Since then, HLA-G was found to be involved in a variety of processes such as viral infection, autoimmune diseases and defined as an immune checkpoint found in most tumors." (PMID 39358558, 2024). "Compelling evidence supports the role of HLA-G in immune tolerance, viral infection, autoimmune diseases and protection of transplanted tissues, via the inhibition of all immune cell effectors (T, B, NK and APC)." (PMID 39358558, 2024).
viral infections (continued). "In healthy conditions, the level of HLA-G expression is restricted to immune-privileged tissues; however, during various viral infections, the upregulation of HLA-G is observed." (PMID 38534374, 2024). "The impact of HLA-G in vertical mother-to-child transmission of viral infection, such as human immunodeficiency virus (HIV) and hepatitis C virus (HCV) infection, has been reported before." (PMID 37504282, 2023). "Human leukocyte antigen G (HLA-G) is one of those immunological co-factors that is supposed to impact the natural history of HPV as well as other viral infections." (PMID 37504282, 2023). "HLA-G and its receptors (LILs) are the best studied molecules present in the placenta barrier and in viral infections that highly modulate the immune microenvironment." (PMID 35877415, 2022). "HLA-G has been found to be expressed under pathological conditions like cancer, autoimmune disease, tissue transplantation, and viral infections." (PMID 34697671, 2022). "The human leukocyte antigen (HLA)-G has been proposed as a possible immunological co-factor in the pathogenesis of HPV as in other viral infections." (PMID 34697671, 2022). "The increased levels of sHLA-G in the presence of the SARS-CoV-2 infection associated with a worse COVID-19 prognosis and death indicates the deleterious role of HLA-G in viral infections." (PMID 36077133, 2022). "It is known that viral infections lead to a decrease in the expression of HLA class I molecules, including HLA-G, allowing NK cells to detect the infected cells and thus be able to perform their cytotoxic function on them." (PMID 35154112, 2022). "Because of these immunomodulatory functions, HLA-G has been involved in several processes, amongst which organ transplantation, viral infections, cancer progression, and autoimmunity." (PMID 35154112, 2022). "The few studies in which male participants were included have mainly focused on exploring HLA-G polymorphism in the HLA-G 3′ untranslated region (UTR) and disclosed an association with other viral infections, such as HCV, HBV, and HIV." (PMID 34697671, 2022). "As summarized in this review, multiple viral infections are known to induce membranous HLA-G expression as well as its secretion in infected host cells." (PMID 35237271, 2022). "Little attention has been devoted to the role of HLA-G in acute emergent viral disorders, especially in biological samples (cerebrospinal fluid and serum) of patients during the infection and in the convalescent phase." (PMID 33776990, 2021). "Broad spectrum immune checkpoint molecules (HLA-G) interact with cytokines, chemokines, and growth factors; however, their roles on acute viral infections must be further scrutinized." (PMID 33776990, 2021). "Human leukocyte antigen-G (HLA-G) is a ligand for multiple immune inhibitory receptors, whose expression can be upregulated by viral infections." (PMID 34938296, 2021). "HLA-G can be upregulated by various viral infections, including SARS-CoV-2, which can render comprehensive immunosuppressive roles in favouring virus immune evasion and subsequent disease progression." (PMID 34938296, 2021). "HLA-G molecules have a complex immune regulatory role in transplantation, cancer, viral infections, chronic inflammatory diseases and pregnancy." (PMID 35082780, 2021). "In certain conditions, like viral infections, the overexpression of HLA-G can create a tolerogenic environment; inhibiting several steps of the immune response, propitiating the spreading of infectious." (PMID 33584667, 2020). "The clinical role of HLA-G has been widely explored in various pathophysiological conditions, such as organ transplantation, viral infection, autoimmune and inflammatory diseases, and cancer." (PMID 32790754, 2020).